IL5 (interleukin 5)
Diseases named in the same sentence as IL5 in open-access papers (continued):
Sharing a sentence is not in itself a finding about the gene and the disease.
eosinophilia (continued). "IL-4 and IL-13 are critically involved in the pathogenesis of allergic asthma by regulating IgE-production by B cells, inducing airway hyperreactivity and triggering key features of airway remodeling, whereas IL-5 is a key factor for eosinophilia." (PMID 18724870, 2008). "As helminthiasis, atopy is the result of aberrant Th2 cytokine response to allergens, with an increased production of IL-4, IL-13, Il-9 and Il-5, with high amounts of allergen-specific and total IgE and eosinophilia." (PMID 19471606, 2008). "At 15 weeks, mice that had inhaled saline in weeks 7–8 developed airway inflammation: eosinophilia (α = 0.05), interleukin-5 (α = 0.05), and AHR (α = 0.05) were greater in ETS mice than in AIR mice." (PMID 17450223, 2007). "Alternatively, IL-10 or TGFβ support Th2 responses that impact on antibody production, mast cell degranulation and eosinophilia via secretion of IL-4, IL-5, IL-10, IL-13." (PMID 17430585, 2007). "In particular, the expression of interleukin-5 (IL-5) by T lymphocytes has been shown to be an essential signal necessary for the induction of eosinophilia in the airway." (PMID 16740158, 2006). "The initial development of eosinophilia is induced in a complex way, including T lymphocyte independent mechanisms, as well as production of IL-5 from CD34+ cells." (PMID 16740158, 2006). "In anotherstudy, elevated levels of both eotaxin and IL-5 in blister fluidof BP were found, suggesting tissue eosinophilia." (PMID 16864900, 2006). "Ablation of the effects of IL-5 has been accomplished with blocking anti-IL-5 antibody, which was accompanied by a reduction in allergen-induced eosinophilia." (PMID 16597326, 2006). "The peak in peripheral eosinophilia at 14–28 DAI reflects the peak of IL-5 mRNA expression observed in the lymphoid tissues of infected jirds." (PMID 16542426, 2006). "Contributing to the maintenance of eosinophilia are cytokines IL5 (interleukin-5) and GM-CSF (granulocyte macrophages colony-stimulating factor), which show up in elevated concentrations." (PMID 16917551, 2006). "In the same manner, the author has genetically manipulated mice, managing to have a line with increase in production of IL-5 and findings of hyper-eosinophilia." (PMID 16446960, 2005). "The suppression of the OVA-induced serum OVA-specific IgE levels, airway eosinophilia and IL-5 levels in the BALF was enhanced." (PMID 15538945, 2004). "This study was undertaken to evaluate the role of IL-5 in eosinophil migration and in the maintenance of eosinophilia in a guinea-pig model of visceral larva migrans syndrome." (PMID 18475693, 1996). "In this study, we evaluated the ability of recombinant human IL-5 (rHu IL-5) to promote tissue eosinophilia and the importance of this eosinophilia to pathological alterations in vascular function." (PMID 18475660, 1995). "She responded favorably to monthly subcutaneous mepolizumab, a monoclonal antibody that prevents interleukin-5 (IL-5) from binding to its receptor, thereby inhibiting the recruitment and activation of eosinophils, with resolution of eosinophilia and improvement in symptoms." (PMID 40755600, 2025). "This complex mechanism is also dependent on the eosinophilia induced by IL-5." (PMID 40305195, 2025). "In contrast to mice treated with the control IgG antibody to SLPI KO mice, SLPI KO mice treated with anti-IL-33 neutralizing antibody showed reduced airway inflammation and fewer numbers of BAL total cells, ratio of eosinophilia, and Th2 cytokines (e.g., IL-5 and IL-13) in BAL fluid." (PMID 40546642, 2025). "Previous reports of iMCD with eosinophilia have demonstrated elevated IL‐5 levels, suggesting that IL‐5 may contribute to the pathophysiology in such cases." (PMID 41439207, 2025). "Whereas IL-5 is critical for eosinophilopoiesis in the bone marrow, it is increasingly recognized that the maintenance of an established tissue eosinophilia may occur independently of IL-5-driven local tissue type 2 signals." (PMID 40498023, 2025).
eosinophilia (continued). "Interestingly, some of these demonstrated that IL-10 can promote the development of airway hyperresponsiveness, mucus metaplasia, IL-5 production, eosinophilia, dendritic cell polarization and a Th2-skewed phenotype in allergic mice." (PMID 39935481, 2025). "Additionally, ILC2s produce cytokines characteristic of T2 inflammation: IL‐4, IL‐5, and IL‐13, contributing to tissue eosinophilia and anti‐helminth immunity." (PMID 40755081, 2025). "IL-3 and IL-5 play a crucial role in the growth, differentiation, and activation of eosinophilia." (PMID 39873807, 2025). "Likewise, paraneoplastic eosinophilia can arise in solid and hematologic malignancies via tumor-derived cytokines (notably interleukin-5), driving recruitment and expansion of eosinophils in peripheral blood." (PMID 41362643, 2025). "Future studies should also determine whether tissue eosinophilia predicts treatment outcomes in patients receiving different monoclonal antibodies targeting type 2 inflammation (e.g., anti–IL-5, anti-IgE)." (PMID 41143090, 2025). "According to literature data, IL‐2 may stimulate IL‐5–producing group 2 innate lymphoid cells, which can, in turn, lead to eosinophilia." (PMID 40145321, 2025). "Notably, airway eosinophilia correlated with IL‐5+ ILC2s at all time points after allergen exposure." (PMID 40755081, 2025). "IL-5-targeting biologics are effective therapeutic agents for reducing eosinophilia." (PMID 39439801, 2024). "The IL5-Tg mouse model is used to study the effect of hyper-eosinophilia." (PMID 38585275, 2024). "A Th2-skewing of T-bet-deficient CD4+ cells may also cause inflammation of the upper respiratory tract, peripheral eosinophilia, and an increase in Th2-cytokines IL-4, IL-5, and IL-13." (PMID 38835658, 2024). "IL-5 is a cytokine that plays a role in regulating eosinophilia activity, and its role in the pathomechanism of multiple sclerosis remains unknown." (PMID 39000506, 2024). "IL-4 enhances mucus and IgE production and stimulates mast cells, while IL-5 promotes eosinophilia." (PMID 39421735, 2024). "Khudhairet al demonstrated thatN. brasiliensis ESPs significantly reduced glucose tolerance and body weight in a mouse model of type 2 diabetes, likely mediated by the increase of eosinophilia and IL-5 in peripheral tissues, showing its therapeutic potential for treating some metabolic disorders." (PMID 39314046, 2024). "Type 2 inflammatory cells are stimulated to produce IL-5, which drives eosinophilia." (PMID 38673059, 2024). "Previous study has suggested that HSP70 may exert protective effects in allergic diseases, such as downregulating eosinophilia, reducing Th2 cytokines (e.g., IL-4, IL-5, IL-13), and lowering allergen-specific IgE levels." (PMID 39640897, 2024). "Although the exact mechanisms underlying DEP-induced lung eosinophilia are unclear, we inferred that DEP-induced eosinophil recruitment to the peripheral lung might be related to an IL-5 independent mechanism." (PMID 38178075, 2024). "This is further in line with previous observations from human TPE patients where eosinophilia (12-fold increase of eosinophils in the lower respiratory tract) was accompanied by increased IL-5 and parasite-specific IgE levels, eosinophil degranulation and retention of MF in the lung tissue." (PMID 38457461, 2024). "In addition, an increase in serum IL-5 levels and peripheral eosinophilia was found in the pediatric population with acute pneumonia relevant to influenza viruses." (PMID 39056079, 2024). "The sputum of patients with COPD concentrations of IL-5 correlates with the degree of eosinophilia." (PMID 39139567, 2024). "A potential link between IL-10 and eosinophilia may be supported by data from IL-10−/− mice showing diminished skin infiltration of eosinophils and IL-4 and IL-5 mRNA expression in a mouse model of allergic dermatitis." (PMID 39076967, 2024).
eosinophilia (continued). "The basis for atopy may stem from an exaggerated Th2 response involving cytokines such as IL-4, IL-5, and IL-13, as well as eosinophilia." (PMID 38742158, 2024). "However, it is believed that eosinophilia results from the tumor’s production of interleukin-5, which is a known main stimulus for eosinophil production in bone marrow." (PMID 39723294, 2024). "Therefore, eosinophilia is considered a Th2-type inflammation related to the activation of IL-5, one of the Th2-type cytokines." (PMID 39200350, 2024). "Laboratory findings for the disease are nonspecific, including leukocytosis, eosinophilia, and the detection of Il-5 in bronchoalveolar lavage fluid, which are all associated with acute eosinophilic pneumonia." (PMID 39028390, 2024). "In addition, CP administration induced IL-5 upregulation by Th2-type cells in the lymph node and spleen, resulting in eosinophilia." (PMID 37631187, 2023). "Additionally, we observed leukocyte morphological changes, eosinophilia, and increased serum levels of IL-2, IL-4, IL-5, and type I and II interferons." (PMID 37766239, 2023). "However, the source of IL-5 or the correlation between blood eosinophilia and lung eosinophilic infiltration remains elusive." (PMID 38259470, 2023). "When assassin lung cytokine modules, no overt Th2 cytokine module was observed in vaccinated and challenged mice exhibiting eosinophilia, a marked difference from small rodent models of VAERD which are characterized by high levels of IL-4, IL-5, and IL-13 and weight loss." (PMID 37600776, 2023). "Compared to RV-A (RV-1B) infection, RV-C (RV-C15) infection induced higher BALF eosinophilia, mRNA expression of IL-5, IL-13, IL-25, Muc5ac and Gob5/Clca, protein production of IL-5, IL-13, IL-25, IL-33 and TSLP, and expansion of ILC2 in naive and HDM-immunized BALB/c mice." (PMID 35386658, 2022). "In early-onset allergic asthma with eosinophilia could be used an anti-IL5/IL5Rα, dupilumab or tezepelumab, but the main reason to choose in first place omalizumab is more years of experience." (PMID 36452259, 2022). "However, IL-33 administration can also induce marked type 2 inflammation, with eosinophilia, increased production of the interleukins IL-4, IL-5 and IL-13 as well as mucus production and epithelium remodeling." (PMID 35844529, 2022). "Two distinct eosinophil subtypes were recently reported with differences in surface protein expression, functions, and response to IL-5, which may explain why eosinophilia has an anti-inflammatory or inflammatory effect in different situations." (PMID 35453584, 2022). "Accordingly, many eosinophils were found in one skin biopsy in which IL-5 expression was detected along with the presence of CD4+ and a low number of CD8+ T cells, and five of the eight subjects showing increased serum IL-5 levels at the time of ADRs had eosinophilia." (PMID 35938810, 2022). "Interestingly, a previous study of Schistosoma mansoni infection reported significantly reduced IL-5 and eosinophilia in mice given the antagonist AMD346571." (PMID 35288645, 2022). "The same treatment also significantly reduced the expression of genes linked to Th2 response and eosinophilia (Il4 and Il5 but not Il13) as well as eosinophil recruitment (Ccl5 and Ccl11) in Atg7fl/fl;Lyz2‐Cre ECRS mice." (PMID 35988262, 2022). "However, studies have shown that airway and/or peripheral blood eosinophilia is attributed to IL-5 stimulation, resulting in the congregation of eosinophils." (PMID 35887589, 2022). "Especially, IL‐5 contributes to eosinophilia, whereas IL‐13 is involved in mucus hypersecretion." (PMID 35344296, 2022). "Eosinophilia was accompanied by large increases in IL-13 and, especially, IL-5." (PMID 35699942, 2022). "Now it is well known that human IL-5 has an impact on the process of eosinophil maturation and may trigger eosinophilia." (PMID 36361964, 2022).
eosinophilia (continued). "Expansion of ILC2s and activation by IL-33 from damaged parenchymal cells results in IL-13 production driving fibrotic gene expression in hepatic stellate cells in fibrosis models, or IL-5 production with resultant hepatic inflammation and eosinophilia in immune-mediated hepatitis models." (PMID 35359972, 2022). "Furthermore, pharmacological inhibition of IL-6 during airway inflammation was associated with a marked local increase in protein levels of IL-13, IL-4, and IL-5, which are critically involved in Th2-mediated eosinophilia." (PMID 35408882, 2022). "Furthermore, we found significantly elevated IL‐5 levels, which suggest markedly increased eosinophilia in the older asthmatic mice." (PMID 34089243, 2021). "Mice with transgenes for IL-5 have high levels of IL-5 and eosinophilia, but remain healthy." (PMID 34912327, 2021). "This strain of mice is characterized by eosinophilia due to increased production of IL‐5." (PMID 33450054, 2021). "Indeed, genetic ablation of IL-5 or its neutralization with monoclonal antibodies abolishes eosinophilia in preclinical models and human patients." (PMID 34576313, 2021). "Mebolizumab is an IL-5 antagonist which reduces eosinophilia." (PMID 35387049, 2021). "Rituximab use might have an impact on IL-5-mediated eosinophilia; further mechanistic studies are required to validate this finding." (PMID 34640595, 2021). "Inhibition of IL-5 with neutralizing antibodies in type-II IFN-deficient mice resulted in reduced survival, indicating that enhanced protection in the absence of type-II IFN was dependent on IL-5 and possibly increased eosinophilia." (PMID 34960631, 2021). "It is plausible that the in utero promotion of lung eosinophilia induced by IL‐5‐producing ILC2 may increase sensory innervation of the airways, wiring them for the development of subsequent airway hyperreactivity." (PMID 34306680, 2021). "IL-5 induces eosinophil development and recruitment, resulting in eosinophilia in the lung." (PMID 33968080, 2021). "This leads to the hypothesis that IL-5 increases the number of IL-5-responsive progenitors and potentiates homing to the tissues, leading to reactive eosinophilia." (PMID 34409272, 2021). "IL-5 is one of these such targets because it is the major cytokine supporting eosinophilia and is responsible for terminal differentiation of human eosinophils, regulating eosinophil proliferation, differentiation, maturation, migration, and prevention of cellular apoptosis." (PMID 33917396, 2021). "These apparent contradictions on the role of IL-5 in basal conditions of tissue-eosinophilia highlight the need for a better characterization of the precise role these lung-resident eosinophils have, especially when translating these findings to the human lung." (PMID 34868033, 2021). "These “anti-eosinophil” biological therapies exploit the dependency of eosinophilia on IL-5." (PMID 34576313, 2021). "In a successful phase IIa study in the allergen challenge model in mild allergic asthmatics, SB010 significantly attenuated early and late asthmatic bronchoconstriction in association with a decrease in Th2-dependent biomarkers including sputum eosinophilia, sputum tryptase, and plasma IL-5 levels." (PMID 33917396, 2021). "Finally, to ascertain that the deletion of IL4Rα in the eosinophils did not affect their abilities to respond to the chemoattractants, we experimentally induced IL-5/eotaxin-mediated lung eosinophilia in the WT and mye-IL4Rα−/− adult mice." (PMID 34326406, 2021). "However, experimental models have demonstrated a role of maternal IL‐5 in airway function by promoting foetal lung eosinophilia." (PMID 34306680, 2021). "Activated intestinal ILC2s produce IL-5 that promotes eosinophilia." (PMID 34122403, 2021). "The efficacy of mAbs targeting IL-5 or its receptor is indisputable in eosinophilic asthma, with more evident clinical results in those patients with a higher percentage of blood and sputum eosinophilia." (PMID 33805199, 2021).
eosinophilia (continued). "Since B cells are involved in the pathogenesis by inducing the release of IL-5 from Th2 cells, an action mechanism of B-cell-depleting therapy in seronegative EGPA myocarditis might include the suppression of IL-5-mediated eosinophilia." (PMID 34640595, 2021). "IL-5 acts on IL-5 receptor subunit α (IL5RA), causing eosinophilia." (PMID 34372824, 2021). "ILC2 activation and resultant Th2 cytokine release is now considered a key event in type 2 inflammatory diseases, with the production and release of IL-5 resulting in eosinophilia, IL-13 resulting in airway mucus production and remodeling, and IL-9 promoting goblet cell hyperplasia and mastocytosis." (PMID 33917396, 2021). "The authors reported that IL-33 deficiency increased S. venezuelensis faecal egg release at day 8 p.i. and simultaneously abrogated lung ILC2 expansion, IL-5 production and lung eosinophilia, while i.n. application of recombinant IL-33 rescued these features in IL-33-/- mice." (PMID 33351862, 2020). "This reduction in IL-5 secretion may be one of the mechanisms by which immunization with Rv3619c, resulted in a reduction in the eosinophilia detected in the BAL fluid and the perivascular and peribronchial eosinophil cellular infiltration." (PMID 33101014, 2020). "Similarly, CpG ODN1826 reduced airway eosinophilia, IL-4 and IL-5 levels, and increased IL-10 when administered during allergen sensitisation." (PMID 33281825, 2020). "CCL8 induced eosinophilia through recruiting IL-5-producing CCR8+Th2 cell in AD murine model." (PMID 32280674, 2020). "This may explain persistent low levels of IL-5 expression, eosinophilia, and airway hyperresponsiveness observed in some of these mouse studies." (PMID 33265990, 2020). "Since tissue eosinophilia is governed by the production of cytokines such as IL-5 and to a lesser extent by IL-13 and IL-4, it is assumed that eosinophilia either in the blood compartment or in the bronchi of asthmatic patients is a reflect of type 2 inflammation." (PMID 32296705, 2020). "In addition to IL-5, eosinophil recruitment and subsequent eosinophilia rely on ILC2 derived IL-13 and stroma derived eotaxin—an essential eosinophil chemokine." (PMID 32079296, 2020). "The production of type 2 cytokines (IL-4, IL-5, IL-10, and IL-13), as well as granulocyte-macrophage colony-stimulating factor (GM-CSF), by these cells induces eosinophilia, M2 macrophage polarization, and the secretion of immunoglobulin G1 (IgG1), IgG4, and IgE." (PMID 33013887, 2020). "Thus, bronchial-epithelial eosinophilia leads to the production of an additional amount of IL-5, and it is an important element for supporting eosinophilic inflammation." (PMID 31885750, 2019). "This may have implications with respect to the use of novel therapeutic agents targeting IL-5 and its receptor in patients with eosinophilia." (PMID 31438916, 2019). "These so-called IL-2 “muteins,” like IL-2 immunocomplexes, may also lead to ILC2 expansion, IL-5 production, and eosinophilia." (PMID 30930900, 2019). "These therapies have been designed to selectively target airway eosinophils, using peripheral blood eosinophil count as a surrogate marker of airway eosinophilia with the assumption that IL-5 mediates its effects via IL-5R found primarily on the surface of eosinophils." (PMID 31415658, 2019). "Additionally, a recent report showed that IL-5-producing ILC2s control eosinophilia induced by IL-2 therapy in humans and mice." (PMID 30930900, 2019). "Moreover, IL-4 has been shown to boost the airway eosinophilia induced by IL-5 in mice sensitized/challenged with OVA." (PMID 31805682, 2019). "Moreover, in these subjects, IL-5-dependent eosinophilia can also contribute to the development of clinically significant comorbidities such as chronic rhinosinusitis with nasal polyps." (PMID 31920718, 2019).